PSMA2 (proteasome 20S subunit alpha 2)
Diseases named in the same sentence as PSMA2 in open-access papers:
PSMA2 is named in the same sentence as 84 diseases in open-access papers, as found by Europe PMC text mining. Sharing a sentence is not in itself a finding about the gene and the disease. The quoted sentences say what the papers report.
breast carcinoma (6 papers, 2017 to 2025). "In basal-like breast cancer, knockdown of PSMA2 was found to be associated with both a significant decrease in cell viability and apoptosis induction." (PMID 33537240, 2020). "High-expressed PSMA family genes (e.g., PSMA2, PSMA3, PSMA4, PSMA6, and PSMA7) in breast cancer tissues are reported to be linked to a poor OS of the cancer, but higher levels of PSMA5 and PSMA8 are indicative of better clinical outcomes." (PMID 41141246, 2025). "Aberrant levels of PSMA2 have also been observed in breast cancer, colorectal cancer, and glioma." (PMID 39794329, 2025). "PSMA2, PSMA3, PSMA4, PSMA6, and PSMA7 showed high expression levels, which were correlated with poor survival of breast cancer patients." (PMID 36424389, 2022). "Furthermore, PSMA2, PSMA3, PSMA4, PSMA6, and PSMA7 showed high expression levels, which were correlated with poor survival of breast cancer patients." (PMID 34943457, 2021). "For both PSMA1 and PSMA2, no datasets revealed significant difference between the breast cancer group and normal tissue group." (PMID 27966459, 2017).
colorectal cancer (6 papers, 2020 to 2025). A primary or metastatic malignant neoplasm that affects the colon or rectum. "In the context of colorectal cancer, PSMA2 enhanced proliferation, migration, and invasion of tumor cells and showed increased expression in stages 1–4; when inhibited, the rate of tumor cell proliferation, which is dependent on iron availability, was dampened." (PMID 38732562, 2024). "For example, PSMA2 enhanced the proliferation, migration and invasion of colorectal cancer." (PMID 38238671, 2024). "Among other selected top co-expressed genes, PSMA2 was found to promote colorectal cancer cell proliferation and NDUFS3 has been reported to be downregulated in the ovarian cancer cell and hypothesized to promote oncogenic development." (PMID 35938038, 2022). "Transfection with si-PSMA2 significantly reduced PSMA2 expression in FHC cells and the two colorectal cancer cell lines." (PMID 33537240, 2020). "Similarly to PSMA2, protease PSMA3 is found to be highly expressed and significantly hindered proliferation, migration, and invasion of tumor cells in colorectal cancer." (PMID 38732562, 2024).
ovarian cancer (6 papers, 2021 to 2025). A primary or metastatic malignant neoplasm involving the ovary. "Our regression analysis identified six genes significantly associated with ovarian cancer: PI3, TFAP2B, MUC7, PSMA2, PIK3C2G, and NME1." (PMID 41154754, 2025). "Additionally, PSMA2 is a protease with established potential as a biomarker for ovarian cancers." (PMID 38732562, 2024). "PSMA2 overexpression is observed in ovarian cancer, and chemokine ligand 9 (CXCL9) is a vascular inhibitor that could inhibit ovarian cancer through lymphocyte invasion." (PMID 38481252, 2024).
Hyperglycemia (4 papers, 2013 to 2024). An increased concentration of glucose in the blood. "For instance, exposure of cervical cancer cells expressing proteasome alpha 2 subunit (PSMA2) to Ex-4 under high glucose conditions led to a significant reduction in tumor volume, highlighting the connection between hyperglycemia and cancer cell proliferation." (PMID 38672620, 2024).
acute myeloid leukemia (3 papers, 2018 to 2025). Acute myeloid leukemia (AML) is a group of neoplasms arising from precursor cells committed to the myeloid cell-line differentiation. "Wang discovered that PSMA2 is related to tumor prognosis in acute myeloid leukemia through weighted gene co-expression network analysis." (PMID 39794329, 2025).
lung carcinoma (3 papers, 2017 to 2025). "High mRNA expression of PSMA1 and PSMA2 was significantly associated with PPS for lung cancer patients, with HR = 0.77 (0.60–0.99), p = 0.043 and HR = 0.65 (0.51–0.84), p < 0.001, respectively." (PMID 27966459, 2017).
cervical cancer (2 papers, 2021 to 2024). A primary or metastatic malignant neoplasm involving the cervix. "Thus, a major question that remain unanswered is how the mechanistic link between GPL-1R and PSMA2 in T2D-linked cervical cancer works, and the relative contribution of both T2D-related hyperglycaemia and inflammation therein." (PMID 33714887, 2021). "Mao and colleagues discovered that prostate specific membrane antigen 2 (PSMA2), a gene found in the proteasome, plays a proto-oncogenic role in promoting the growth of cervical cancer cells." (PMID 39429275, 2024). "Moving forward, it will be important to unravel the basic mechanisms involved in the relationship between the co-expression of PSMA2 and GLP-1R in T2D-linked cervical cancer, and their downregulation by Exendin-4." (PMID 33714887, 2021). "They discovered an elevated co-expression of GLP-1R and PSMA2 in cervical cancer models, both in humans and experiments, that could be reduced by exendin-4." (PMID 39429275, 2024). "In this context, it should be noted that the knockdown of GLP-1R in human and mouse cervical cancer cell lines led to the corresponding downregulation of PSMA2, implying a direct effect, independent of the glucose-lowering function of Exendin-4." (PMID 33714887, 2021).
Parkinson disease (2 papers, 2023). A progressive degenerative disorder of the central nervous system characterized by loss of dopamine producing neurons in the substantia nigra and the presence of Lewy bodies in the substantia nigra and locus coeruleus. "Previous reports have identified PSMA2 as a potential peripheral biomarker for the early diagnosis of Parkinson’s disease." (PMID 37240016, 2023). "Dysfunction of PSMA2 may contribute to neuronal dysfunction and neurodegenerative diseases such as Parkinson’s disease." (PMID 37240016, 2023).
type 2 diabetes (2 papers, 2019 to 2024). "For example, the association between PSMA2 and cancer and type 2 diabetes has been demonstrated, suggesting its critical position in tumorigenesis." (PMID 39682314, 2024).
asthma (1 paper, 2023). "In asthma, PSMA2 expression causes inflammation by activating the NF‐κB and producing inflammatory cytokines." (PMID 38018577, 2023).
bladder cancer (1 paper, 2017). "For bladder cancer, Oncomine included only four datasets that were available for cancer vs. normal analysis, of which Dyrskjot and Sanchez-Carbayo's dataset respectively showed elevated expression levels of PSMA2 and PSMA5 in bladder cancer compared to normal tissues." (PMID 27966459, 2017).
endothelial dysfunction (1 paper, 2025). In vascular diseases, endothelial dysfunction is a systemic pathological state of the endothelium (the inner lining of blood vessels) and can be broadly defined as an imbalance between vasodilating and vasoconstricting substances produced by (or acting on) the endothelium. "The increased expression of the proteasome degradation pathway members, PSMA2 and PSMB1, might also explain the even more pronounced endothelial dysfunction in male compared to female mice." (PMID 41190220, 2025).
esophageal cancer (1 paper, 2021). A primary or metastatic malignant neoplasm involving the esophagus. "Interestingly, other proteasome subunits were also expressed highly in EC and the elevated expression of PSMA2, PSMA5, PSMC6, PSMD5, PSMD10 indicated poor prognosis of EC patients respectively, which revealed a crucial role of 26S proteasome in esophageal cancer." (PMID 33897885, 2021).
Hepatic steatosis (1 paper, 2023). Steatosis is a term used to denote lipid accumulation within hepatocytes. "Thus an upregulation of the components of the proteasome complex PSMA2 and PSMB8, in the presence of HK4 might lead to proper protein degradation and avoid accumulation of misfolded proteins, which could otherwise cause hepatic steatosis." (PMID 36860523, 2023).
lung carcinoid tumor (1 paper, 2017). A neuroendocrine neoplasm that arises from the lung. "Two comparisons of Bhattacharjee's dataset indicated that the PSMA2 mRNA levels were higher in small cell lung cancer and lung carcinoid tumor tissues than in normal samples." (PMID 27966459, 2017).
pulmonary fibrosis (1 paper, 2023). Chronic progressive interstitial lung disorder characterized by the replacement of the lung tissue by connective tissue, leading to progressive dyspnea, respiratory failure, or right heart failure. "In IPF, TGF‐β increases the expression of proteasome 20S subunit alpha 2 (PSMA2), leading to inflammation and pulmonary fibrosis." (PMID 38018577, 2023).
tularemia (1 paper, 2020). Tularemia is an infection caused by the bacterium Francisella tularensis. "At Day 7, a change in proteasome subunit alpha type-2 (PSMA2), known to be involved in MHC Class I antigen presentation, was increased from pre-vaccination and was associated with the tularemia-specific microagglutination titer." (PMID 32722207, 2020).
vitiligo (1 paper, 2024). Generalized well circumscribed patches of leukoderma that are generally distributed over symmetric body locations and is due to autoimmune destruction of melanocytes. "The role of EEF2, EEF1G and PSMA2 in vitiligo or inflammation pathways remains unclear." (PMID 38715599, 2024).
cancer (14 papers, 2014 to 2025). A tumor composed of atypical neoplastic, often pleomorphic cells that invade other tissues. "Collectively, these results indicated that PSMA2 is elevated in OSCC and higher expression is associated with a poorer prognosis, supporting a potential role of PSMA2 in cancer recurrence." (PMID 39794329, 2025). "As for PSMA2, all 24 datasets with statistical significance revealed higher expression levels of PSMA2 in cancer tissues than in normal tissues." (PMID 27966459, 2017). "Using our extensive pan-cancer NK cell atlas, we were able to generate a solely NK cell-derived, tissue-residency signature (atlas-TR: PSMA2, SLC5A3, CCL4L2, CLN3, SCGB1A1, AREG), which outperformed the conventional literature-derived TR signature across tissue and tumor type." (PMID 38956379, 2024). "The functions of PSMA2 in tumorigenesis have been revealed in numerous human cancers." (PMID 33537240, 2020). "Similar to our findings using microarray analysis, FoxO was necessary for the cancer-induced upregulation of Cebpb, Fos, Fbxo31 and Psma2, and was necessary for the cancer-induced downregulation of Col6a2, Myoz3 and Tnc (interaction effect, p < 0.05, AAV9-ev C26 vs. AAV9-d.n.FoxO C26, p < 0.05)." (PMID 25539728, 2014). "Immunohistochemistry results indicated significant upregulation of GALP, CACNA1C, COL16A1, PENK, C4BPA, PSMA2, and CXCL9 in cancer tissues." (PMID 38481252, 2024). "Immunohistochemistry results indicated significantly elevated GALP, CACNA1C, COL16A1, PENK, C4BPA, PSMA2, and CXCL9 expression in cancer tissues." (PMID 38481252, 2024). "Although the literature has separately confirmed the dysregulation of each gene of the PSMA family that was individually observed in various types of cancer, along with their involvement in other tumor-related issues, only PSMA1 and PSMA2 have so far appeared as potential candidates." (PMID 34943457, 2021). "As far as we know, there is no report about PSMA2/miR-132 in human cancer." (PMID 33537240, 2020).
tumor (12 papers, 2017 to 2026). "The overexpression of PSMA2 significantly augmented tumor growth of KOSC3 xenografts in vivo, supporting the oncogenic property of PSMA2 in OSCC tumorigenicity." (PMID 39794329, 2025). "The results showed that PSMA2-overexpressing KOSC3 cells exhibited a reduction in metformin IC50, from 3.92 to 2.05 mM, compared to control cells, and the treatment significantly suppressed PSMA2-induced tumor growth." (PMID 39794329, 2025). "Collectively, the findings revealed positive correlations between PSMA2 and signature genes involved in various tumor-promoting functions, particularly those related to cell cycle regulation and mitochondrial dysfunction." (PMID 39794329, 2025). "Furthermore, a prior study demonstrated that PSMA2 may indirectly affect tumor cells through the immune microenvironment." (PMID 40426895, 2025). "To verify the specific role of macrophage and tumor cell polyamine metabolism in tumor progression, we detected the levels of PSME2 and PSMA2 in early THCA and locally invasive THCA tissue samples." (PMID 40390766, 2025). "When grouped by tumor stage, all seven PSMAs showed different prognostic values in stage 1, whereas only PSMA1, PSMA2 and PSMA5 were correlated with OS or PPS in stage 2." (PMID 27966459, 2017). "We hypothesize that altered expression of PSMA2 provides a direct link between mitochondrial dysfunction and OSCC tumor progression and recurrence, due to defects in mitophagy and fail to degrade excessive or damaged mitochondria." (PMID 39794329, 2025). "Within tumor tissue in the adequate iron group, and more so in tumors from the excess iron diet group, we found there was also significantly greater (p ≤ 0.05) expression of proteins involved in protein degradation (ANPEP, DPP7, ITGB1, PSMA1, PSMA2, PSMA3, and SERPINB1)." (PMID 38732562, 2024).
infection (10 papers, 2017 to 2025). The state of being infected such as from the introduction of a foreign agent such as serum, vaccine, antigenic substance or organism. "Some previous studies have shown that expression of PSMA2 was upregulated in A549 cells after infection with highly pathogenic IAV strains or in primary bronchial airway epithelial cells by PR8 infection." (PMID 35019712, 2022). "Based on the dysregulated proteins, IPA predicted that PR8 infection could cause significant downregulation of the NRF2-mediated signaling pathway (Z-score = −2 [Fig. 5B1]) but a significant upregulation of this pathway by PSMA2 KD (Z-score = +2.44 [Fig. 5B2])." (PMID 35019712, 2022). "However, in this study, we detected a significantly lower expression of PSMA2 in A549 cells after PR8 infection." (PMID 35019712, 2022). "Interestingly, IPA could predict that 61 (1 upregulated and 60 downregulated) pathways were significantly reregulated by PSMA2 KD+PR8 infection." (PMID 35019712, 2022). "HSPA5 KD, PSMA2 KD and IGFBP5 KD remained stable throughout the course of infection." (PMID 36680137, 2022). "Among them, 17 diseases and functions were significantly dysregulated by either PR8 infection alone or PSMA2 KD+PR8 infection but not by others." (PMID 35019712, 2022). "Thus, PSMA2 KD may affect IAV replication by influencing inflammation and cell cycle regulation during infection." (PMID 35019712, 2022).
PSMA2 also shares sentences with these, for which no sentence is quoted: Hypertension (8 papers); Anxiety (6); Sepsis (6); delirium (5); glaucoma (5); respiratory depression (4); Ataxia (3); Arrhythmia (2); attention deficit and hyperactivity disorder (2); COVID-19 (2); familial hemiplegic migraine (2); Gastrointestinal dysmotility (2); glioma (2); myelodysplastic syndrome (2); Tics (2); amyotrophic lateral sclerosis (1); antiplasmin deficiency (1); anxiety disorder (1); Arthritis (1); bladder incontinence (1); cardiac arrest (1); cardiovascular disease (1); cerebral autosomal recessive arteriopathy with subcortical infarcts and leukoencephalopathy (1); chronic periodontitis (1); coagulation disorder (1); connective tissue disorder (1); corneal ulcer (1); Crohn disease (1); delirium tremens (1); dementia (1).
A further 33 diseases each share a sentence with PSMA2 in 1 paper.